COL4A4 (collagen type IV alpha 4 chain)
Diseases named in the same sentence as COL4A4 in open-access papers (continued):
Sharing a sentence is not in itself a finding about the gene and the disease.
Alport syndrome (continued). "Inheritance of Alport syndrome is X-linked (OMIM301050), autosomal recessive (OMIM 203780), digenic (typically with a pathogenic variant in each of COL4A3 and COL4A4) or autosomal dominant (OMIM 104200, or thin basement membrane nephropathy, due to heterozygous COL4A3 or COL4A4 variants)." (PMID 33854215, 2021). "Mutations in COL4A3, COL4A4 and COL4A5 genes lead to Alport syndrome (AS)." (PMID 34508137, 2021). "Occurrence of Alport syndrome is caused by mutations in COL4A3, COL4A4, or COL4A55." (PMID 34675305, 2021). "In addition, multiple studies have shown that patients with FSGS were reclassified as Alport syndrome based on mutations found in COL4A3, COL4A4, and COL4A5." (PMID 31921302, 2019). "Variants in COL4A4 gene lead to the formation of abnormal or non-functional type IV collagen which eventually results into Alport syndrome (AS) [MIM# 203780] or thin basement membrane nephropathy [MIM# 141200]." (PMID 30745910, 2018). "My proposal is that patients with hematuria, thin GBM, and a mutation inCOL4A3, COL4A4, orCOL4A5 have a form of Alport syndrome and that patients without such mutations have “hematuria with thin GBM”." (PMID 28163907, 2017). "In many families a cause is not identified, however, in 40–50% cases, TBMN is linked with a heterozygous mutation of the COL4A3, COL4A4 or COL4A5 genes that encode type IV collagen, and the clinical features overlap with the carrier state for autosomal recessive or X-linked Alport syndrome." (PMID 27190376, 2016). "In particular, mutations in the type IV collagen α5 chain gene (COL4A5) are responsible for the X-linked form of the disease, which accounts for ~85% of the patients and mutations in the type IV collagen α3 or α4 chain gene (COL4A3 or COL4A4) lead to the autosomal form of the Alport syndrome." (PMID 26555339, 2015). "Vitreoretinal degeneration is complicated by retinal detachment in Alport syndrome, leading us to speculate that aberrations in COL4A4 may be involved in retinal thinning in cases of lattice degeneration of the retina." (PMID 22723992, 2012). "The precise prevalence of Alport syndrome in the US is uncertain, but estimates of the prevalence of heterozygous pathogenic variants in these genes are ~1 in 100 individuals for either COL4A3 or COL4A4, and ~1 in 2000 individuals for hemizygous or heterozygous variants in COL4A5." (PMID 40317772, 2025). "Renal damage is the most life-threatening symptom of X-linked Alport syndrome (XLAS), an inherited disease caused by X-linked COL4A5 gene mutations, which cause more than 80% of all Alport syndrome cases (the remaining cases are caused by COL4A3/COL4A4 gene mutations)." (PMID 40075271, 2025). "However, the 2 most commonly affected genes (COL4A3 and COL4A4) have no extrarenal associations in AD Alport syndrome but are associated with hearing loss and ocular abnormalities in the much less common AR Alport syndrome." (PMID 40303230, 2025). "For instance, Alport syndrome (AS) is a progressive hereditary renal disease accompanied by sensorineural hearing loss and ocular abnormalities, caused by the pathogenic variants in the genes of COL4A3, COL4A4, and COL4A5 encoding type IV collagen α3, α4, and α5 chains, respectively." (PMID 36685964, 2022). "Alport syndrome (AS) is a progressive hereditary kidney disease accompanied by sensorineural hearing loss and ocular abnormalities caused by disease-causing mutations in the COL4A3, COL4A4, and COL4A5 genes, which encode type IV collagen α3, α4, and α5 chains, respectively." (PMID 36013122, 2022). "The relationship is less clear for severe heterozygous COL4A3 or COL4A4 variants in AD Alport syndrome since kidney failure is not common and may be due to coincidental disease." (PMID 35602506, 2022).
Alport syndrome (continued). "While pathogenic COL4A5 variants cause x-linked Alport syndrome and bi-allelic mutations in COL4A3 or COL4A4 cause the autosomal recessive form, the interpretation of the biological significance of rare pathogenic but heterozygous COL4A3 or COL4A4 mutations can be challenging." (PMID 31049720, 2020). "It provides the disease confirmation or exclusion, identification of atypical Alport syndrome, determination of symptomatic and asymptomatic monoallelic COL4A3, COL4A4, and COL4A5 carriers (especially COL4A5 females), and inheritance pattern establishment." (PMID 40004525, 2025). "Currently, the most accurate method for diagnosing Alport syndrome is comprehensive parallel genetic testing of the entire coding sequences of the COL4A3, COL4A4, and COL4A5 genes using next-generation sequencing (NGS)." (PMID 40004525, 2025). "Recent advances in genetic analysis have enabled comprehensive and efficient screening of multiple genes including COL4A3, COL4A4, and COL4A5 for patients suspected as having Alport syndrome." (PMID 35211492, 2022). "The members of the extracellular matrix structural constituent, COL4A3, COL4A4 and COL4A5, have been reported to be consistent with digenic inheritance and, together, lead to the occurrence of Alport syndrome." (PMID 35804365, 2022). "First, the clinical relevance of genes detected in our screen, CUBN and COL4A4, is underscored by a respective monogenic disease featuring albuminuria and kidney disease, Imerslund-Grasbeck (MIM 261100) and Alport syndrome (MIM 203780)." (PMID 31511532, 2019). "The clinical features in Alport syndrome are explained because the COL4A5 and COL4A3/COL4A4 genes code for the collagen IV α5 chain, α3 and α4 chains which form a heterotrimer in the basement membranes of the glomerulus, cochlea and eye." (PMID 27627812, 2016). "The allele distributions of three polymorphisms already described in previous studies related to Alport syndrome (D326Y in COL4A3 and M1327V and F1644F in COL4A4) were significant for the KC patient cohort." (PMID 20029656, 2009). "Some genes that can mimic ADPKD, such as COL4A3, COL4A4, and COL4A5 associated with Alport syndrome, were not standardly included as part of the analyses for individuals in these studies." (PMID 41509997, 2026). "While maternal carrier status for an X‐linked Alport syndrome gene variant (COL4A5) was disclosed, P/LP variants in COL4A3 or COL4A4 were not reported unless both partners had at least one variant." (PMID 40317772, 2025). "First, this patient had heterozygous variants in COL4A4 and not COL4A5, which is known to be associated with a worse prognosis, especially in males with X-linked Alport syndrome." (PMID 41299396, 2025). "Overall, the commonest genes affected in FSGS are COL4A5 (XL Alport syndrome) and COL4A3 and COL4A4 (usually AD rather than the rare AR Alport syndrome) INF2, TRPC6 and ACTN4." (PMID 37578539, 2024). "The three collagen IV genes involved in Alport syndrome are COL4A3, COL4A4, and COL4A5." (PMID 38745975, 2024). "Future studies will focus on confirming more closely a genotype-phenotype correlation using proteinuria rather than kidney failure in women with X-linked Alport syndrome and in individuals with heterozygous COL4A3 or COL4A4 pathogenic variants." (PMID 35602506, 2022). "With AR Alport syndrome, two severe variants in COL4A3 or COL4A4 have a more damaging effect than one or none." (PMID 35602506, 2022). "However, recent expert consensus guidelines recommend genetic confirmation as essential, defining Alport syndrome more broadly to include all individuals harboring pathogenic variants in COL4A3, COL4A4, or COL4A5, regardless of their clinical presentation." (PMID 40852417, 2025). "Since the kidney cysts in Alport syndrome and the no-mutation-detected subtype of ADPKD are usually smaller and fewer than typical ADPKD, the role of COL4A3 and COL4A4 in tubular basement membrane might be only minor in the cystogenesis." (PMID 41450889, 2025).
Alport syndrome (continued). "In conclusion, we have reported for the first time two cases of X-linked Alport syndrome where the only structure affected by a decrease in COL4A5 immunolabeling was Bowman’s capsule and where neither COL4A3 nor COL4A4 could have thus been at cause." (PMID 38668984, 2024). "In the LOVD database, the age at kidney failure was not different for AR and for X-linked Alport syndrome (24.4 ± 7.8 years, n = 237, p = 0.39), and in the case of AR disease, was not different for COL4A3 (23.2 ± 9.3, n = 35, p = 0.45) or COL4A4 (25.4 ± 10.3, n = 26, p = 0.55) variants." (PMID 35602506, 2022). "We found there were no clinical features of Alport syndrome not only in six probands with c.2858G>T(p.(G953V)) in COL4A5 plus pathogenic variants in other genes (e.g., WT1, ADCK4, NPHP1, TRPC6, COL4A4, and PAX2) but also in another six probands with only the c.2858G>T(p.(G953V)) variant." (PMID 31576025, 2020). "A new form of digenic non-Mendelian inheritance of Alport syndrome, with coexisting mutations in COL4A3, COL4A4, or COL4A5 genes, has recently been described, simulating autosomal recessive inheritance (digenic mutations in trans) or autosomal dominant inheritance (mutations in in cis mode)." (PMID 33233744, 2020). "Genetic testing is now the gold standard investigation, with next-generation sequencing of COL4A3, COL4A4, and COL4A5 being recommended in patients with no family history of Alport syndrome." (PMID 41299396, 2025). "However, another group of authors who conducted a similar analysis of a large cohort of patients with dominant forms of Alport syndrome (COL4A3 and COL4A4) before our study did not observe statistical differences between the sexes." (PMID 36013122, 2022).
thin basement membrane nephropathy (21 papers, 2013 to 2025). "Thin basement membrane nephropathy (TBMN) is often attributable to mutations in the COL4A3 or COL4A4 genes that encode the α3 and α4 chains of type IV collagen, respectively, a major structural protein in the glomerular basement membrane." (PMID 26833262, 2016). "Individuals with heterozygous COL4A3 or COL4A4 mutations usually have Thin basement membrane nephropathy with normal renal function but some develop renal impairment." (PMID 27627812, 2016). "A systematic review of 777 thin basement membrane nephropathy/ADAS patients with a single mutation (COL4A3/COL4A4) showed that the prevalence of ESRD in this population was 15.1%, compared to a prevalence of 62% in patients with ARAS and 70% in male patients with XLAS." (PMID 34858896, 2021). "About 40–50% of patients with familial microscopic hematuria (FMH) caused by thin basement membrane nephropathy (TBMN) inherit heterozygous mutations in collagen IV genes (COL4A3, COL4A4)." (PMID 29764427, 2018). "The clinical phenotypes of heterozygous mutations in COL4A3 and COL4A4 are heterogeneous, and can cause autosomal dominant AS (ADAS), thin basement membrane nephropathy (TBMN), focal segmental glomerulosclerosis (FSGS) and benign familial hematuria (BFH)." (PMID 28542346, 2017). "In addition, there were 83 individuals heterozygous for one of these variants, with 70 (84%) heterozygous for p.Gly533Asp in COL4A4 and 13 (16%) for p.Gly139Arg in COL4A3, consistent with the diagnosis of AD AS or thin basement membrane nephropathy." (PMID 36844206, 2023).
focal segmental glomerulosclerosis (18 papers, 2016 to 2025). A renal disorder characterized by sclerotic lesions in the glomeruli. "Recent sequencing studies show that the phenotypic spectrum of rare COL4A4 mutations extends to focal segmental glomerulosclerosis, which typically presents with proteinuria." (PMID 31511532, 2019). "The nephrotic syndrome/focal segmental glomerulosclerosis sequencing panel detected a heterozygous, likely pathogenic variant in COL4A4 (c.2842G>T)." (PMID 30002862, 2018). "While the first patient underwent WES, which detected a pathogenic variant in COL4A5, the second patient had a nephrotic syndrome/focal segmental glomerulosclerosis sequencing panel that revealed a likely pathogenic variant in COL4A4." (PMID 30002862, 2018). "Pathogenic variants in COL4A4 or COL4A3 genes were frequently found in patients with focal segmental glomerulosclerosis (FSGS)." (PMID 36982595, 2023). "Among the most common pathogenic variants were COL4A3, COL4A4, COL4A5, and other genes that are implicated in focal segmental glomerulosclerosis." (PMID 38993907, 2023). "Heterozygous mutations in COL4A4 or COL4A3 genes are frequent among patients with microscopic hematuria of glomerular origin and have been confirmed in patients with focal segmental glomerulosclerosis." (PMID 36982595, 2023). "Heterozygous COL4A3 or COL4A4 variants, or heterozygous COL4A5 in women can present with a range of histological and phenotype features variably, including hematuria, proteinuria, focal segmental glomerulosclerosis, and chronic kidney disease." (PMID 37180518, 2023). "Recent findings by us and others showed that about 50% of patients with COL4A3/COL4A4 heterozygous mutations, a prevalent cause of familial microscopic hematuria due to TBMN, develop proteinuria with secondary focal segmental glomerulosclerosis (FSGS), after their third decade of life." (PMID 28334007, 2017). "The results of her sister’s tissue diagnosis are unknown; however, the possibility of focal segmental glomerulosclerosis due to a COL4A4 pathogenic variant cannot be ruled out." (PMID 38765603, 2024). "Pathogenic variants in the COL4A3, COL4A4, and COL4A5 genes lead to collagen IV (COL4) nephropathies, including Alport syndrome (AS), thin basement membrane nephropathy, and familial forms of focal segmental glomerulosclerosis (FSGS)." (PMID 39588246, 2024). "In focal segmental glomerulosclerosis (FSGS) patients, COL4A3 and COL4A4 were frequently not tested, resulting in a missed molecular diagnosis in some patients and inappropriate genetic counseling." (PMID 36925663, 2023).
Nephropathy (16 papers, 2012 to 2025). A nonspecific term referring to disease or damage of the kidneys. "While COL4A5 gene variants cause X-linked AS, mutations in COL4A3 or COL4A4 genes (both located on chromosome 2) are associated with autosomal recessive AS, autosomal dominant AS, and thin basement membrane nephropathy." (PMID 41306271, 2025). "Based on the identified responsible variant, COL4A4-associated nephropathies, a sub-classification of the conditions in the two pedigrees, is strongly recommended." (PMID 36699462, 2022). "Our finding broadens mutation spectrum of the COL4A4 gene and extends the phenotypic spectrum of collagen IV nephropathies." (PMID 27469977, 2016). "Results after re-sequencing of 103 samples with mutations in COL4A3 or COL4A4 genes and thin basement membrane nephropathy." (PMID 22319602, 2012). "Our case suggests that the cystic change may manifest as a subtype of WT1-related nephropathy, particularly when the second modifier, such as COL4A4 variant, coexists." (PMID 41450889, 2025). "Although no cystic appearance has previously been reported in children with WT1 p.Arg467Gln, our findings raise the possibility that the COL4A4 variant may contribute to a cystic phenotype in WT1 nephropathy." (PMID 41450889, 2025). "The role of the heterozygous COL4A4 VUS variant in the cystic formation of WT1-related nephropathy kidney remains unclear." (PMID 41450889, 2025). "On the other hand, disease-causing variants may be found less frequently in COL4A3 and COL4A4, because these cohorts include individuals with possibly other causes of persistent microscopic haematuria, including IgA, post-streptococcal and C3 nephropathy." (PMID 35260866, 2022). "Interestingly, the index patient’s grandmother was initially diagnosed with IgAN and the unexpected identification of the co-segregating COL4A4 [c.G2636A (p.Gly879Glu)] mutation in her suggested co-existence of a collagen IV-related nephropathy." (PMID 25381091, 2014). "Further functional studies of the COL4A3/COL4A4 mutations and application of in vitro and/or in vivo models with genetic deficiency are warranted to facilitate a better understanding of the pathogenesis and development of effective treatments for collagen IV nephropathies." (PMID 27469977, 2016). "Alport syndrome (AS) is a clinically heterogeneous nephropathy caused by pathogenic variants in collagen IV genes (COL4A3, COL4A4, COL4A5) with a prevalence of 1:5.000." (PMID 35260866, 2022). "Finally, for the heterozygous COL4A3/COL4A4 pathogenic variants carriers, our data are consistent with a recent systematic review on COL4A3/COL4A4 nephropathy, in which the rate of ESRD is 15.1% at a mean age of 52.8 years." (PMID 33369211, 2021). "This study identified a novel heterozygous mutation (NM_000092 c.2030G>A, p.G677D) of the collagen type IV alpha‐4 gene (COL4A4), which may broaden the phenotypic spectrum of type IV collagen nephropathies." (PMID 33159707, 2020). "For this reason, we need to change the definition of AS to include all cases with nephropathy caused by COL4A3, COL4A4, or COL4A5 gene variants and eliminate the disease entity of TBM; this will allow patients to avoid missing the opportunity to start appropriate treatment as early as possible." (PMID 30128941, 2019). "COL4A3/COL4A4‐associated TBMN, FSGS and AS may be more appropriate to be classified as collagen IV nephropathies." (PMID 27469977, 2016). "In addition, we also recommended the new classification of collagen IV nephropathies, which may be a benefit to the diagnosis, target drug treatment, and management of patients with COL4A3/COL4A4 mutations." (PMID 33159707, 2020). "In addition, together with previous studies, we also recommended the new classification of collagen IV nephropathies, which may be a benefit to the diagnosis, target drug treatment, and management of patients with COL4A3/COL4A4 mutations." (PMID 33159707, 2020).
Nephropathy (continued). "Therefore, COL4A3/COL4A4‐associated TBMN, FSGS and AS may be better classified as subtypes of collagen IV nephropathies, caused by collagen IV abnormalities, because of the clinical overlap and multiple mutations of the same gene in this group of disorders." (PMID 27469977, 2016). "Given the same genetic lesion, the COL4A3/COL4A4 related FSGS, AS and GBM related diseases should be classified as subtypes of collagen IV nephropathies, which have been encouraged in previous reports." (PMID 33159707, 2020).